ALKBH5 (alkB homolog 5, RNA demethylase)
Diseases named in the same sentence as ALKBH5 in open-access papers (continued):
Sharing a sentence is not in itself a finding about the gene and the disease.
tumor (continued). "Alkbh5 modulates Mct4/Slc16a3 expression, lactate content and the composition of tumor-infiltrating Treg and myeloid derived suppressor cells." (PMID 38779665, 2024). "In the lower DEGs in tumours with low ALKBH5 expression, 14 KEGG pathways were significantly enriched (FDR < 0.05)." (PMID 39127986, 2024). "ALKBH5‐RIP assay identified lncRNA CARMN as a direct target of ALKBH5 in human tissue and mouse xenograft tumours." (PMID 39039912, 2024). "ALKBH5 is a tumour suppressor that is lowly expressed in some tumours and can behave as a tumour suppressor in an m6A‐dependent manner." (PMID 39163517, 2024). "ALKBH5-KO B16 tumors exhibited reduced expression of Mct4/Slc16a3, lactate content in the tumor-infiltrating fluid (TIF), and decreased abundance of myeloid-derived suppressor cells (MDSCs) and regulatory T cells (Tregs) within TME." (PMID 39199429, 2024). "Correlation analysis results demonstrated that ALKBH5 correlated positively with HSPA4 while negatively with CD58 in GC tumor tissues." (PMID 38589927, 2024). "IHC result showed that FSH increased expression of N-cadherin, ALKBH5, Snail and decreased expression of E-cadherin in tumor tissues, while these effects were reversed by the knockdown of ALKBH5." (PMID 38505602, 2024). "Despite the fundamental importance of m6A in cancer, the exact clinical relevance of ALKBH5 remains elusive as ALKBH5 protein and mRNA expression have been shown to be both increased or decreased in tumours compared to normal tissue." (PMID 39127986, 2024). "Cell–cell contact interactions between ALKBH5 high-expression or low-expression tumor cells with CD8+ T cells were analyzed by CellChat v.1.5.0 package." (PMID 38589927, 2024). "Pyrazolo [1,5-a]pyrimidine Derivative DDO-2728 had also been found to act as a selective inhibitor of ALKBH5, significantly suppressing tumor growth in the MV4-11 xenograft mouse model (Wang YZ." (PMID 39220683, 2024). "Fourteen significantly enriched pathways with down-regulated DEGs in tumours with low ALKBH5 expression were identified." (PMID 39127986, 2024). "ALKBH5 also inhibits tumor growth and tumor migration by decreasing the activity and expression of YAP in NSCLC, ultimately leading to apoptosis in NSCLC cells." (PMID 38785921, 2024). "The results showed that the expression of FTO and ALKBH5 was higher in NPC patients with tumor node metastasis (TNM) stages III and IV than in NPC patients with TNM stages I and II." (PMID 38263362, 2024). "In 2020, both Wang and Shen reported an indispensable role for ALKBH5 in maintaining the self-renewal of AML tumor stem cells." (PMID 38711100, 2024). "Changes in the activity of key methylases such as METTL3 and ALKBH5 can significantly affect the response of tumor cells to chemotherapy and radiotherapy." (PMID 39473440, 2024). "ALKBH5 is a demethylase and increasing evidence has shown that ALKBH5 is closely related to tumor growth, proliferation, and survival." (PMID 39281280, 2024). "There is growing evidence that FTO and ALKBH5 are promising new treatment targets for several human disorders, particularly tumours." (PMID 38572667, 2024). "A tumor-suppressive effect of ALKBH5 was detected in pancreatic cancer by preventing its progression by activating period circadian regulator 1 (PER1), which in turn inhibited cell growth." (PMID 38503745, 2024). "In conclusion, these data proved that the ALKBH5–apoptosis axis has a vital effect on MM tumorigenesis and inhibits tumor development and progression." (PMID 38785921, 2024). "We then measured the effects of ALKBH5 on colony formation, tumour formation and invasion, expectedly, it is presented that, knockdown of ALKBH5 significantly decreased all these phenomena." (PMID 38098223, 2024).
tumor (continued). "Genes higher in tumours with low ALKBH5 expression were significantly enriched (FDR < 0.05) in the cytokine-cytokine receptor interaction pathway." (PMID 39127986, 2024). "Additional research has found that the m6A RNA demethylase ALKBH5 affects the accumulation of Tregs and MDSCs in the tumor microenvironment by regulating the expression of Mct4/Slc16a3 and lactate content, thereby influencing the response to anti-PD-1 therapy." (PMID 39654883, 2024). "Conversely, overexpression of ALKBH5 reduces tumor cell proliferation and invasion while promoting enhanced tumor growth." (PMID 39192357, 2024). "For instance, the hypoxia-induced m6A demethylase alkB homolog 5 (ALKBH5) removes m6A and stimulates tumor macrophage recruitment and tumor immune escape through epigenetic and epitranscriptomic upregulation of CXCL8 in glioblastoma." (PMID 37198402, 2023). "ALKBH5 plays a key role in regulating the proliferation, invasion, and migration of tumor cells by catalyzing RNA demethylation." (PMID 38072944, 2023). "Studies have revealed that ALKBH5 functions as a tumor promotor in GBM, gastric cancer, ovarian cancer and AML." (PMID 36810108, 2023). "To investigate the function of ALKBH5 in HCC, we first measured the protein level of ALKBH5 in 67 pairs of patient tumor and adjacent tissues." (PMID 36609413, 2023). "IHC staining assays demonstrated that knocking down LINC00659/ALKBH5 decreased JAK1 expression in tumours, while overexpressing LINC00659/ALKBH5 increased the expression of JAK1." (PMID 36864711, 2023). "Depletion of tumor-intrinsic ALKBH5 enhanced m6A modification on PD-L1 mRNA, and promoted its degradation in a YTHDF2-dependent manner." (PMID 36810108, 2023). "Here, we demonstrated that ALKBH5 was up-regulated in pNENs and played a critical role in tumor growth and lipid metabolism." (PMID 37858219, 2023). "ALKBH5 can exert both carcinogenic and tumor-suppressive effects, depending on the specific cancer type." (PMID 38094306, 2023). "Overexpression of ALKBH5 can reduce tumor proliferation, metastasis, and invasion activity in vitro and inhibit tumor growth in vivo." (PMID 38072944, 2023). "GO analysis was performed using 541 significantly upregulated genes of tumour samples with the lowest and highest ALKBH5 expression from ACRG." (PMID 36864711, 2023). "Consistent with the in vitro findings, hypoxic areas of tumor tissue showed relatively high ALKBH5 expression in the xenograft mouse model." (PMID 37149664, 2023). "Dysregulated in numerous malignancies, ALKBH5 plays oncogenic or antitumor roles as an m6A demethylase, depending on the tumor type." (PMID 36810108, 2023). "A study of melanoma showed that ALKBH5 regulates the recruitment of tumor-infiltrating regulatory T cells (Tregs) and MDSCs by modulating the density of m6A marks and the number of splicing events during ICB therapy." (PMID 37217462, 2023). "IHC assays showed decreased expression of Ki‐67 (a key biomarker in tumour growth) and suppressed expression of ALKBH5 in the shALKBH5‐1 and shALKBH5‐2 groups, which were consistent with the WB results." (PMID 36864711, 2023). "miR‐3190 in BM‐EVs is transferred into orthotopic tumor cells and enhances their metastatic capacity by downregulating AlkB homolog 5 (ALKBH5) expression." (PMID 37096833, 2023). "ALKBH5 deletion alters the metabolic profile of tumor cells and reduces lactate levels in the tumor immune microenvironment by altering the splicing and expression of target genes (Mct4/Slc16a3) via an m6A-dependent mechanism." (PMID 37485079, 2023). "To explore the function of ALKBH5 in vivo, we construct the tumor xenograft models using QGP-1 cells with ALKBH5 knockdown." (PMID 37858219, 2023). "ALKBH5 restrained tumor growth and metastasis by downregulating YTHDFs-mediated YAP expression and suppressing miR-107/LATS2–mediated YAP activity in NSCLC." (PMID 37919739, 2023).
tumor (continued). "To investigate the potential role of ALKBH5 in pNENs, we initially examined the expression of ALKBH5 in tumor tissues and normal tissues by using an immunohistochemistry." (PMID 37858219, 2023). "It has been found that ALKBH5 targets the transcript of the lactate acid reporter Mct4 in tumours to elevate mRNA levels, enhancing extracellular lactate concentrations and the recruitment of Tregs and MDSCs in the TIME." (PMID 36859310, 2023). "Knockdown of the m6A demethylase gene (ALKBH5) enhanced the sensitivity of tumor cells to immunotherapy." (PMID 37272931, 2023). "ALKBH5 plays a crucial role in various human malignancies, mainly through m6A-dependent post-transcriptional regulation of oncogenes of tumor suppressors." (PMID 37007161, 2023). "Another deep impressed study unveiled that upregulation of ALKBH5 inhibited cell proliferation and tumor growth in TC." (PMID 37915103, 2023). "ALKBH5 knockdown promotes glucose uptake in TC xenografts through activation of circNRIP1-mediated glycolytic functions of tumor cells by sponging oncogenic miR-541-5p and miR-3064-5p as well as by upregulating pyruvate kinase M2 (PKM2) levels." (PMID 37915103, 2023). "We found that the volumes, weights and growth rate of xenografted tumours significantly increased compared to control group when ALKBH5‐overexpressed cells were implanted." (PMID 37203239, 2023). "In this study, we demonstrated for the first time that RNA demethylases FTO and ALKBH5 were aberrantly upregulated in uLMS and exhibited an essential tumor-promoting role in uLMS." (PMID 37175660, 2023). "Specimen analysis further confirmed that tumours with high levels of ALKBH5 were more sensitive to anti-PD1 therapy." (PMID 36859310, 2023). "ALKBH5 knockdown in GSCs significantly reduced proliferation and tumour sphere formation in GSC cell lines." (PMID 37444417, 2023). "In conclusion, ALKBH5 has a low expression in TC and exhibits a tumor-suppressive effect through m6A modification-mediated epigenetic regulation." (PMID 37915103, 2023). "We confirmed that ALKBH5 overexpression within tumor lesions increased the expression of the proliferation marker Ki67 while reducing CHAC1 expression." (PMID 38007439, 2023). "ALKBH5 can modulate Mct4/Slc16a3 expression and lactate content of the tumor microenvironment to regulate the composition of tumor‐infiltrating Treg and myeloid‐derived suppressor cells." (PMID 36260366, 2023). "ALKBH5 regulates the effect of immunotherapy via modulating lactate levels and suppressive immune cell accumulation in the tumor microenvironment." (PMID 37742191, 2023). "Unlike FTO, which is involved in the regulation of IFN-γ-mediated cytokine and chemokine pathways, ALKBH5 mainly affects the recruitment of immune cells in tumor microenvironment." (PMID 37264402, 2023). "Based on three bioinformatics methods, we analysed the entire TCGA database and found significant upregulation of ALKBH5 in 414 GC tumour samples compared to 37 normal samples." (PMID 36864711, 2023). "Knockout of FOXM1-AS also destroyed FOXM1 expression and self-renewal in GSCs, and overexpression of FOXM1 can rescue tumor growth of GSCs after depletion of ALKBH5 or FoxM1-AS, which further disclosed the key role of FOXM1 in GSCs initiated tumorigenesis." (PMID 36683086, 2023). "Tumor cells spread from the footpad to the popliteal fossa, and those with high ALKBH5 expression had more metastases." (PMID 36632222, 2023). "Just like the role of FTO in the pathogenesis of TC, ALKBH5 also regulates ferroptosis and glycolysis, thus affecting the tumor progression." (PMID 37915103, 2023). "ALKBH5 was shown to enhance the enrichment of BCSCs in the hypoxic tumor microenvironment, and this was also demonstrated in immunodeficient mice." (PMID 37007137, 2023). "Given the key roles mediated by MMP2 and MMP9 in tumor metastasis, their association with MALAT1 and ALKBH5 was subsequently investigated." (PMID 37639643, 2023).
tumor (continued). "Growing evidence has shown that FTO- and ALKBH5-mediated m6A demethylation is involved in various tumours, displaying biological context-dependent functions." (PMID 36859310, 2023). "Further experiments indicated that ALKBH5 exerted its pro-tumor role in lung tissue through upregulating FOXM1." (PMID 35628623, 2022). "Recently, the roles of ALKBH5 in various biological processes have been confirmed, such as cell proliferation, tumor invasion and metastasis, and osteogenesis." (PMID 35784864, 2022). "Some m6A regulators are abnormally expressed in OC, such as YTHDF1, YTHDF2, METTL3, ALKBH5 etc., and promote or disrupt the development or maintenance of tumour phenotypes." (PMID 35303965, 2022). "This can be achieved by in vivo delivery of ALKBH5 gene into the target tumor cells by vectors based on retroviruses, adenoviruses or adeno-associated viruses (AAVs)." (PMID 35063010, 2022). "Various m6A methylation enzymes, such as METTL3, FTO, and ALKBH5, clearly affect key cellular processes in tumor cells, including apoptosis, resulting in resistance to radiation therapy." (PMID 35794625, 2022). "Mounting evidence shows that ALKBH5 plays critical roles in a variety of human malignancies, mostly via post-transcriptional regulation of oncogenes or tumor suppressors in an m6A-dependent manner." (PMID 35063010, 2022). "Conversely, deletion of ALKBH5 attenuates the immunosuppressive function of MDSCs and enhances the efficacy of tumor immunotherapy." (PMID 35794625, 2022). "ALKBH5 in tumor cells recruits immune suppressive cells, including myeloid-derived suppressor cells (MDSCs) and Tregs, and facilitates lactate accumulation to regulate the anti-PD-1 therapy response depending on m6A in melanoma." (PMID 35720276, 2022). "Our results suggested that targeting ALKBH5 improved the tumor immune microenvironment and enhanced the efficacy of anti-PD-1 therapy through the acceleration of PD-L1 degradation, which provides a promising combination therapeutic strategy for GBM." (PMID 36566230, 2022). "The hypoxic microenvironment enriches stemness characteristics and CSCs levels through stimulating HIF and ALKBH5 expression in tumor cells." (PMID 35794625, 2022). "In ICC, tumor-intrinsic ALKBH5 removes m6A modification in PDL1 mRNA’s 3′UTR and reduces its degradation in a YTHDF2-dependent manner, thus inhibiting cytotoxicity of T cells and mediating immune escape of ICC cells." (PMID 35063010, 2022). "A demethylase, alkylation repair homolog protein 5 (ALKBH5), is one type of N6-methyladenosine (m6A) eraser that plays a tumor-suppressive role in a variety of cancers." (PMID 35517412, 2022). "ALKBH5 regulates the expression of Mct4/Slc16a3 and the content of lactic acid in tumor microenvironment, as well as the composition of Tregs and bone marrow-derived suppressor cells." (PMID 35590394, 2022). "For instance, breast cancer is associated with transcriptional activity of ALKBH5 mediated by HIF-1α and HIF-2α, leading to a decrease in m6A modification on NANOG mRNA and initiation of the tumor in the hypoxic TME." (PMID 35804965, 2022). "Taken together, we used our NB tissue samples and cells to validate the capability of glucometabolic gene signature and the potential tumor suppressive role of ALKBH5." (PMID 35517412, 2022). "ALKBH5 deficiency decreased PD-L1 protein level by suppressing ZDHHC3 mRNA expression in an m6A modification manner, further remodeling the tumor immune microenvironment." (PMID 36566230, 2022). "In short, this paper demonstrated that ALKBH5 functioned as a tumor suppressor in PC through modulating transcriptional fate via the ALKBH5/m6A/YTHDF2/PER1 axis." (PMID 35628623, 2022). "For example, ALKBH5 inhibits tumor growth and metastasis by reducing the expression and activity of YAP in non-small cell lung cancer." (PMID 35093087, 2022). "Overall, we have identified ALKBH5 as a tumor suppressor in GC metastasis, and this role is dependent on the demethylase activity of ALKBH5." (PMID 35114989, 2022).
tumor (continued). "Apart from tumor-intrinsic ALKBH5–PD-L1 regulating axis, accumulating evidence confirmed the critical role of ALKBH5 in remodeling immune microenvironment in cancer." (PMID 35063010, 2022). "ALKBH5 was first reported to promote tumor stem formation in gliomas and subsequently reported to promote tumor progression in breast and colon cancer." (PMID 35982895, 2022). "It was reported that ALKBH5 and m6A demethylase deletion increased tumor cell sensitivity to immunotherapy and that m6A demethylases in tumor cells contribute to the efficacy of immunotherapy." (PMID 36761423, 2022). "ALKBH5 has been reported to be dysregulated with either tumor-promoting or tumor-inhibiting roles in various cancer types." (PMID 35395767, 2022). "In the setting that ALKBH5 functions as a tumor suppressor, inhibiters targeting negative regulators of ALKBH5 demonstrate great pharmacological potential as cancer remedy." (PMID 35063010, 2022). "The positive expression of Ki67 and NANOG, OCT4, and SOX2 proteins was found to be decreased in the tumor tissues of mice treated with Exos-sh-NC, which was further reduced in the presence of Exos-sh-ALKBH5." (PMID 36551544, 2022). "The IHC results were consistent with the transcriptome data in the TCGA database, indicating that the protein expression level of ALKBH5 in GC tumor tissues was lower than that in adjacent normal tissues." (PMID 36686788, 2022). "We also highlighted advances in ALKBH5-targeting approaches and the related clinical potential in tumor therapy." (PMID 35063010, 2022). "Conversely, the over-expression of ALKBH5 dramatically suppressed proliferation, migration, and invasion of PC cells, and reduced tumor volume in the PC xenograft model." (PMID 35628623, 2022). "In the present study, we showed that the knockout of m6A demethylase ALKBH5 dramatically inhibited tumor growth in immune-complete mice with increased infiltration of T cells in xenograft." (PMID 36566230, 2022). "m6A demethylase ALKBH5 accelerated the process of ovarian carcinogenesis through NF-κB pathway in a simulated tumor microenvironment." (PMID 36545327, 2022). "The number of polymorphonuclear MDSCs (PMN-MDSCs) are decreased in Alkbh5-KO tumors and MDSCs depletion attenuates tumor growth, which suggest that the regulation of immunosuppressive MDSCs recruitment via Alkbh5 is indispensable during GVAX/anti-PD-1 therapy." (PMID 36439186, 2022). "Data from human malignancies suggest a contradictory role for ALKBH5: that of an oncogene in some cancers and that of a tumor suppressor in other cancer types." (PMID 35063010, 2022). "Together, these results indicate that ALKBH5 inhibition has a protective effect on tumour growth in vivo." (PMID 35414790, 2022). "The RNA levels of most m6A regulators were significantly different between normal and tumor samples, with 22 genes upregulated and ALKBH5 downregulated in tumor tissues." (PMID 35223837, 2022). "ALKBH5 exerts tumor-promoting roles in the development and maintenance of AML and self-renewal of leukemia stem/initiating cells (LSCs/LICs) through post-transcriptional regulation of its key target TACC3, AXL." (PMID 35784761, 2022). "Further investigation showed that ALKBH5 modulated Mct4 expression and induced lactate content, thereby reducing immune cell populations in the tumor microenvironment during GVAX vaccination and anti-PD-1 antibody therapy." (PMID 35628623, 2022). "To explore the role of ALKBH5 in tumor development, we knocked down ALKBH5 expression in HN4 and Cal27 cells using small interfering RNA (siRNA)." (PMID 35395767, 2022).